CRP (C-reactive protein)
Diseases named in the same sentence as CRP in open-access papers (continued):
Sharing a sentence is not in itself a finding about the gene and the disease.
rheumatoid arthritis (continued). "In patients with rheumatoid arthritis and ankylosing spondylitis, the levels of SOD, MDA, erythrocyte sedimentation rate, and C-reactive protein (CRP) were measured." (PMID 40867576, 2025). "In this case, the patient’s weakly positive anti-CCP antibodies, number of small and large joint involvement, and mildly elevated CRP strongly supported a diagnosis of RA, based on ACR/EULAR 2010 Rheumatoid Arthritis Classification Criteria, despite her negative RF status." (PMID 40709149, 2025). "Rheumatoid arthritis results in an increase in serological biomarkers such as ACPA, CRP, IL-1β, IL-6, and TNF-α." (PMID 40136507, 2025). "C-reactive protein (CRP) is an acute-phase inflammatory protein whose expression increases in response to inflammation, including in conditions such as rheumatoid arthritis, various cardiovascular diseases, and infections." (PMID 40871731, 2025). "Comparison of anti-CarP, CRP, and ESR between rheumatoid arthritis patients and healthy controls by Welch’s one-way ANOVA." (PMID 39092366, 2024). "Another investigation revealed that the NBS supplement, administered orally to rats with rheumatoid arthritis, significantly reduced serum levels of inflammatory markers such as ESR and CRP." (PMID 38522056, 2024). "In clinically unremitting rheumatoid arthritis patients, serum LYVE1 levels were positively correlated with CRP." (PMID 38135837, 2024). "There is also a linear correlation between clinical and laboratoristic parameters of RA and periodontitis, such as the high Disease Activity Score Calculator for Rheumatoid Arthritis (DAS28), RF, ACPAs, CRP, ESR, and disease duration." (PMID 38139057, 2023). "In another study on patients with rheumatoid arthritis, the CAR significantly positively correlated with CRP and ESR." (PMID 35505647, 2022). "ZFTG can effectively regulate the levels of inflammatory indicators such as CRP in the blood of rats by mediating the TLR2/4-NF-κB signaling pathway and relieving the symptoms of arthritis in the feet of rats with rheumatoid arthritis." (PMID 36188596, 2022). "Both Erythrocyte Sedimentation Rate (ESR) and blood levels of C-Reactive Protein (CRP) are elevated in various infectious and inflammatory conditions, like systemic lupus erythematosus and rheumatoid arthritis." (PMID 35144674, 2022). "An actual meta-analysis of 737 patients showed that statin therapy significantly improved the disease activity score (DAS28), tender joint count, erythrocyte sedimentation rates (ESR), and C-reactive protein (CRP) in patients with rheumatoid arthritis (RA) relative to placebo." (PMID 36035406, 2022). "In rheumatoid arthritis, t-VNS resulted in reductions in disease activity, CRP, interferon-γ, and interleukin-10, but hitherto, such transcutaneous devices have not been explored in the treatment of PsA or AS." (PMID 34135691, 2021). "Receiver-operating characteristic analysis of C-reactive protein (CRP), erythrocyte sediment rate (ESR) and calprotectin from patients with Rheumatoid arthritis (RA) and healthy individuals (HCs)." (PMID 34160468, 2021). "Other selected features include differential diagnoses for RA (e.g., juvenile rheumatoid arthritis, osteoporosis, psoriasis) and lab tests for diagnosing or monitoring RA (e.g., cyclic citrullinated peptide, c-reactive protein, and erythrocyte sedimentation rate)." (PMID 34707226, 2021). "RA: rheumatoid arthritis; SLE: systemic lupus erythematosus; OA: osteoarthritis; GA: gouty arthritis; CRP: C-reactive protein; ESR: erythrocyte sedimentation rate." (PMID 34136020, 2021). "In patients excluded, we observed significantly greater preoperative CRP and FAR in patients with either a chronic inflammatory condition (rheumatoid arthritis) or those necessitating a revision TKA for a periprosthetic infection." (PMID 33592030, 2021).
rheumatoid arthritis (continued). "Circulating chemerin levels are increased in various inflammatory diseases such as rheumatoid arthritis and correlate to disease activity and to several circulating pro-inflammatory markers, such as TNF-α, IL-6, and CRP." (PMID 34639186, 2021). "In patients with rheumatoid arthritis (RA), inflammatory biomarkers, such as TNF-α or C-Reactive Protein, were inversely correlated to VB6 level in sera, but again VB6 medication in non-deficient subjects showed no beneficial effect." (PMID 34205653, 2021). "The good agreement indicated between DBS and the reference method at low to mid-range CRP could pave the way for development of self-sampling blood collection devices as part of novel remote monitoring services available to individuals living with chronic diseases such as rheumatoid arthritis." (PMID 33273485, 2020). "A positive correlation between increased CRP and radiographic deformities of the TMJ was found for rheumatoid arthritis in previous studies, and is thereby in line with literature." (PMID 32069957, 2020). "Although there is a positive correlation between CRP and SAA concentrations, studies have shown that SAA can be a more sensitive marker of inflammation in certain diseases, such as rheumatoid arthritis, primary biliary cirrhosis, and chronic active hepatitis." (PMID 32245401, 2020). "Only a few studies have reported the NLR, PltLR, and MLR as measurement tools of inflammation in rheumatoid arthritis and reported that these markers are correlated with DAS28, ESR, and CRP." (PMID 32429264, 2020). "Another study showed that higher CRP levels correlated with lower levels of TC, LDL-C, and HDL-C in patients with rheumatoid arthritis." (PMID 32684941, 2020). "Based on a Romanian retrospective study in 2015, CRP and ESR levels significantly decreased for patients with rheumatoid arthritis during treatment with biological therapy." (PMID 32512854, 2020). "An inverse relationship between platelets and CK was found in one study on rheumatoid arthritis, together with increases in inflammatory clinical markers such as ESR and CRP." (PMID 30974900, 2019). "BAIAP2L1 has also been shown in the disease progression of rheumatoid arthritis, where BAIAP2L1 expression in fibroblast-like synovial cells was positively correlated with C-reactive protein (CRP), a common clinical marker for inflammation." (PMID 26222696, 2015). "Olendzki and colleagues, in a study of patients with rheumatoid arthritis, showed a slight (modest) but significant decline in ESR and CRP compared to the baseline values." (PMID 26925896, 2015). "Rheumatoid arthritis (RA) is an acute inflammatory condition in joint with functional impairments mainly involved with localized (skeletal join) excessive prostaglandin synthesis as well as systemic inflammation characterized by increased level of serum CRP." (PMID 26180591, 2015). "Increased serum resistin in patients with rheumatoid arthritis correlated with both C-reactive protein (CRP) and DAS28, suggesting a role of this adipokine in the pathogenesis of rheumatoid arthritis." (PMID 22910888, 2012). "We calculated the correlations between advanced glycation end-product levels in rheumatoid arthritis sera and the Disease Activity Score 28 (DAS28), age, disease duration, CRP, anti-CCP, rheumatoid factor and treatment with corticosteroids, respectively." (PMID 20433772, 2010). "Rheumatoid arthritis was ruled out based on negative rheumatoid factor (RF < 20 IU/mL), normal CRP, and normal ESR (7 mm/hr)." (PMID 41589093, 2026). "In addition, saffron was shown to improve levels of ESR, CRP, TNF-alpha, MDA, and TAC in patients with rheumatoid arthritis when given at a daily dosage of 100 mg." (PMID 40365184, 2025). "The results of the meta-analysis demonstrated a statistically significant difference between the rheumatoid arthritis group and the control group, showing that curcumin may reduce ESR, CRP, RF, and DAS28." (PMID 41470771, 2025).
rheumatoid arthritis (continued). "Data including audiometric results, medical histories, autoimmune and inflammatory markers (ANA, RF, ESR, CRP, ACA, ANCA), and autoimmune diseases such as Ankylosing Spondylitis (AS), Hypothyroidism (HT), Rheumatoid Arthritis (RA), and Systemic Lupus Erythematosus (SLE) were analyzed." (PMID 40281315, 2025). "Furthermore, CRP is used in the monitoring of chronic disease, for example as a component of the DAS-28 instrument for monitoring rheumatoid arthritis and so the long-term variation of CRP is clinically important." (PMID 41284612, 2025). "However, exercise has been shown to enhance muscle mass and decrease levels of inflammatory markers, such as TNF-α, C-reactive protein (CRP), and IL-6, in patients with rheumatoid arthritis (RA)." (PMID 38822418, 2024). "Adiponectin levels did not correlate with CRP in patients with rheumatoid arthritis and patients with Crohn’s disease." (PMID 38791005, 2024). "C-reactive protein (CRP) and erythrocyte sedimentation rate (ESR) are commonly used laboratory markers of systemic inflammation, typically elevated in inflammatory joint diseases like rheumatoid arthritis." (PMID 39206165, 2024). "It has been reported that MLR levels are increased in various systemic autoimmune diseases such as Sjögren's syndrome, rheumatoid arthritis, systemic lupus erythematosus, and ankylosing spondylitis, and there is a positive correlation between acute phase reactants of MLR such as CRP and ESR." (PMID 37731441, 2023). "It has been shown that synovial fluid (SF) calprotectin as a biomarker was superior to neutrophil counts in SF and serum CRP levels to discriminate septic arthritis from non-septic inflammatory arthritis diseases such as gout and rheumatoid arthritis." (PMID 37396347, 2023). "A study performed on 99 rheumatoid arthritis patients observed a negative correlation between capillary density and CRP levels." (PMID 37370974, 2023). "ALT, alanine aminotransferase; AST, aspartate aminotransferase; CRP, C-reactive protein; DAS28, disease activity score 28; ESR, erythrocyte sedimentation rate; KL, Kellgren–Lawrence; OA, osteoarthritis; RA, rheumatoid arthritis; RF, rheumatoid factor; TLC, total leukocyte count." (PMID 37644537, 2023). "For example, CRP is less likely to be elevated under anti-IL-6 receptor antibody therapy in patients with rheumatoid arthritis since the release of CRP is affected by IL-6; therefore, it is not useful for assessing disease activity." (PMID 38002777, 2023). "The activity of rheumatoid arthritis was assessed using erythrocyte sedimentation rate (ESR), C-reactive protein (CRP), protein, disease activity score (DAS), rheumatoid factor (RF), Visual Analogue Scale (VAS) pain, tender joint count (TJC) and swollen joint count (SJC)." (PMID 37325651, 2023). "Conventional biomarkers for rheumatic diseases, especially C-reactive protein (CRP) and erythrocyte sedimentation rate (ESR), have shown excellent correlation to disease activity in adult diseases such as rheumatoid arthritis and ankylosing spondylitis and are regularly used in clinical practice." (PMID 35964131, 2022). "Moreover, eNAMPT appears upregulated in autoimmune diseases, exemplarily, rheumatoid arthritis, psoriasis, or inflammatory bowel disease, whereas serum levels of eNAMPT could be correlated with the commonly determined inflammation parameters C-reactive protein (CRP) and IL-6." (PMID 35250621, 2022). "Even among rheumatoid arthritis (RA) patients with a Disease Activity Score in 28 joints (DAS28) C-reactive protein (CRP) remission, a proportion of 74–77% does not achieve “true” Boolean remission." (PMID 35629033, 2022). "A further trial showed a decrease in CRP concentrations in individuals adhering to a vegan diet compared to a non-vegan diet control group, in individuals with rheumatoid arthritis." (PMID 36558530, 2022).
rheumatoid arthritis (continued). "Circulating IL-37 levels have been found to positively correlate with levels of CRP and/or ESR in patients with rheumatoid arthritis, systemic lupus erythematosus, adult-onset Still’s disease, ankylosing spondylitis, gout, and osteoarthritis, as well as in patients with chronic heart failure." (PMID 34367169, 2021). "We aimed to establish the frequency of HLA-B27 in AS patients by flow cytometry and relate the differences between B27+ and B27- cases to the serum concentrations of rheumatoid arthritis factor (RA), erythrocyte sedimentation rate (ESR), and C-reactive protein (CRP)." (PMID 33791178, 2021). "Swollen 28-joint count (SJC-28), Tender 28-joint count (TJC-28), CRP, erythrocyte sedimentation rate (ESR), uncarboxylated osteocalcin (UCOC), MMP-3, TNF, IL-6, and DAS28-ESR (Diseases Activities Score-28 for Rheumatoid Arthritis with ESR) levels are also decreased." (PMID 34770980, 2021). "The meta-analysis of randomized controlled trials showed that NSAIDs, the first line medicine for the AGA, had no direct effect on the CRP level in rheumatoid arthritis and ankylosing spondylitis which both are inflammatory arthritis." (PMID 33292329, 2020). "Also, RF positivity, SJC-28, TJC-28, CRP, erythrocyte sedimentation rate (ESR), uncarboxylated osteocalcin (ucOC), MMP-3, TNF-α, IL-6, disease Activity Score-28 for Rheumatoid Arthritis with ESR (DAS28-ESR) levels were alleviated." (PMID 31013659, 2019). "In rheumatoid arthritis (RA), IL-22 responses are increased in peripheral blood and joints, IL-22 induces RANKL, and the magnitude of IL-22 response correlates with inflammatory markers (ESR and CRP), RA disease activity scores and degree of bone damage." (PMID 24676270, 2014). "The inverse correlation of both PGD2 and expression of hPGDS in mDCs in SF with the markers of systemic disease activity (CRP and ESR) suggests that systemic disease activity may be influenced by actions of PGD2 in rheumatoid arthritis and other arthropathies." (PMID 23737645, 2013). "In rheumatoid arthritis, CRP levels are increased, and this correlates well with disease activity but in SpA, CRP is usually not a good guide for inflammation." (PMID 23657512, 2013). "The levels of both antigens in rheumatoid arthritis sera did not correlate with age, gender, corticosteroid treatment, or levels of CRP, anti-CCP antibodies, and rheumatoid factor in sera." (PMID 20433772, 2010). "Previous studies have suggested that conventional surrogate markers for disease activity in rheumatoid arthritis and psoriatic arthritis, such as erythrocyte sedimentation rate and levels of C-reactive protein (CRP) are not useful for chronic plaque psoriasis." (PMID 19266104, 2009). "In patients with rheumatoid arthritis (RA), curcumin significantly reduced the ESR (MD: 29.47; 95%CI: 54.05, −4.88; I2 = 99%) and CRP levels (MD: 0.93; 95%CI: 1.33, −0.53; I2 = 89%) as compared to the control group." (PMID 40538540, 2025). "Saffron was found to improve erythrocyte sedimentation rate (ESR), CRP, TNF-alpha, malondialdehyde (MDA), and total antioxidant capacity (TAC) levels in rheumatoid arthritis (RA) patients when administered 100 mg daily." (PMID 40365184, 2025). "RA, rheumatoid arthritis; OS, Okomarigoto sheet; MS, morning stiffness; DAS28-CRP, disease activity score using 28-joint count- C-reactive protein; CDAI, Clinical Disease Activity Index; SDAI, Simplified Disease Activity Index." (PMID 40135026, 2025). "To gain insight into the involvement of rheumatological biomarkers in the course and severity of RA, we evaluated the expression of a set of known serum diagnostic markers of rheumatoid arthritis, mainly ACPA, ESR, CRP and RF, which are sensitive but not specific markers for RA." (PMID 38919260, 2024). "The C-reactive protein (CRP) level was used as an exposure factor, and rheumatoid arthritis (RA) was used as a positive control." (PMID 38835791, 2024).
rheumatoid arthritis (continued). "* p = <0.05; n, number; NA, not available; %, percentage; SD, standard deviation; ACPA: anti-citrullinated peptide antibodies; CRP: C-reactive protein; ESR: erythrocyte sedimentation rate; RA: rheumatoid arthritis." (PMID 37746389, 2023). "In addition, CRP may be elevated due to many factors unrelated to IBD, such as infection, rheumatoid arthritis, and autoimmune diseases." (PMID 37041496, 2023). "In addition, vitamin B6, one of the E-DII components, exhibited a negative correlation with CRP, consistent with the findings from patients with rheumatoid arthritis and elderly men." (PMID 36615742, 2022). "In addition, CRP is not a specific parameter for infection-induced inflammation, as it can be increased in systemic autoimmune diseases, such as rheumatoid arthritis." (PMID 35926065, 2022). "Resveratrol has shown anti-rheumatoid arthritis properties by decreasing rheumatoid arthritis patients’ swelling, tenderness and disease activity via decreasing the biochemical markers of inflammation such as MMP-3, ESR, C-reactive protein, IL-6 and undercarboxylated osteocalcin." (PMID 36551806, 2022). "In rheumatoid arthritis (RA), mostly erythrocyte sedimentation rate (ESR) and C-reactive protein (CRP) are routinely assessed." (PMID 35986420, 2022). "Resveratrol shows its anti-rheumatoid arthritis properties with reduced RA patients’ swelling, tenderness, and disease activity by lowering the biochemical indicators of inflammation like MMP-3, IL-6, ESR, C-reactive protein, and undercarboxylated osteocalcin." (PMID 35237163, 2022). "The second objective of the study is to relate the differences between B27+ and B27- cases to the serum concentrations of rheumatoid arthritis factor (RA), erythrocyte sedimentation rate (ESR), and C-reactive protein (CRP)." (PMID 33791178, 2021). "Nevertheless, accumulating evidence indicates that CRP also plays an important role in some autoimmune diseases, such as systemic lupus erythematosus (SLE), rheumatoid arthritis (RA) and EAE." (PMID 33841391, 2021). "Third, the possibility of other concurrent collagen diseases that might elevate CRP such as primary sclerosis cholangitis and rheumatoid arthritis was not excluded, and such diseases may have confounded the results." (PMID 34797817, 2021). "Receiver-operating characteristic analysis of C-reactive protein (CRP), erythrocyte sediment rate (ESR) and calprotectin from patients with Rheumatoid arthritis (RA) and Osteoarthritis (OA)." (PMID 34160468, 2021). "IL-23 levels were found to be positively correlated with other inflammatory biomarkers such as C-reactive protein (CRP) and rheumatoid factor in rheumatoid arthritis (RA) patients." (PMID 34834482, 2021). "It is also well known that certain common autoimmune disorders, e.g., rheumatoid arthritis, may not necessarily increase CRP levels." (PMID 31561355, 2019). "This is positively correlated to C reactive protein (CRP) and is a strong predictor of mortality in both the general population and for patients with rheumatoid arthritis (RA)." (PMID 28634698, 2018). "Recent data from the Brigham and Women’s Hospital Rheumatoid Arthritis Sequential Study (BRASS), a prospective observational RA cohort, highlights the improvements in HDL-C efflux capacity with reductions in high sensitivity CRP." (PMID 30886961, 2018). "As expected, CRP and ESR normalized after the initiation of tocilizumab, and stayed so throughout the whole treatment period in all patients except for one female patient with rheumatoid arthritis, who had an arthritic relapse after 6 months of TCZ-SC (CRP 1.50 mg/dl)." (PMID 30258504, 2018). "Workshop participants also sought further evidence on the risks of not prescribing based on POC CRP and guidance in the application of test results to different populations, including children and patients with comorbidity (such as rheumatoid arthritis and chronic obstructive pulmonary disease)." (PMID 26940107, 2016).